MYL1 (myosin light chain 1)
Description:
Non-regulatory myosin light chain required for proper formation and/or maintenance of myofibers, and thus appropriate muscle function.
Synonyms: MLC1; MLC1F; MLC3F; MLC-1; MLC1/3; CMYO14; CMYP14; MYOFTA
Tractability: PROTAC: ubiquitination databases record sites on it.
Gene: Protein-coding gene on chromosome 2 (210,290,150 to 210,315,174, reverse strand). Ensembl gene ENSG00000168530.
Pathways (Reactome):
Muscle contraction: Striated Muscle Contraction
Gene Ontology:
Molecular function: structural constituent of muscle; microfilament motor activity; calcium ion binding
Biological process: muscle contraction; actin filament-based movement; muscle filament sliding
Cellular component: myofibril; contractile muscle fiber; cytosol; muscle myosin complex; myosin II complex; sarcomere
Genetic constraint (gnomAD): Loss-of-function variants: 15 observed, 21.73 expected, observed/expected ratio (o/e) 0.69, 90% interval 0.46 to 1.06. The upper end of that interval is the gene's LOEUF score, 1.06, which puts it in group 4 of 6, group 1 being the genes least tolerant of losing a copy. Missense variants: 230 observed, 239.75 expected, observed/expected ratio (o/e) 0.96, 90% interval 0.86 to 1.07. Synonymous variants: 96 observed, 86.93 expected, observed/expected ratio (o/e) 1.1, 90% interval 0.94 to 1.31.
Gene-disease validity (ClinGen):
ClinGen rates the evidence that MYL1 causes each of these diseases.
congenital myopathy (autosomal recessive): Limited.
Homologues: Orthologues: chimpanzee MYL1 (98% identical), guinea pig MYL1 (94% identical), mouse Myl1 (91% identical), tropical clawed frog myl1 (82% identical), macaque MYL1 (79% identical), rabbit MYL1 (78% identical), dog MYL1 (77% identical), rat Myl1_v1 (75% identical), pig MYL1 (72% identical), zebrafish myl1 (62% identical), zebrafish mylz3 (48% identical), Drosophila melanogaster Mlc-c (40% identical), and 2 more. Paralogues in human: MYL3 (70% identical), MYL4 (69% identical), MYL6B (66% identical), MYL6 (57% identical).
Diseases named in the same sentence as MYL1 in open-access papers:
MYL1 is named in the same sentence as 26 diseases in open-access papers, as found by Europe PMC text mining. Sharing a sentence is not in itself a finding about the gene and the disease. The quoted sentences say what the papers report.
congenital myopathy (4 papers, 2020 to 2025). "Our findings confirm that bi‐allelic MYL1 variants are associated with a severe congenital myopathy, characterised by a distinctive clinical and histopathological phenotype involving impaired type II fibre development." (PMID 40488356, 2025). "To date, only two individuals have been reported with biallelic pathogenic MYL1 variants, presenting with congenital myopathy and respiratory insufficiency (#618414; CMYP14)." (PMID 40488356, 2025). "MYL1‐related congenital myopathy is an ultra‐rare and severe condition, associated with a deficiency of essential/alkali light myosin and impaired development of fast‐twitch type II muscle fibres." (PMID 40488356, 2025). "In this study, we present two individuals from unrelated families with a severe congenital myopathy associated with biallelic variants in the MYL1 gene." (PMID 40488356, 2025). "This study describes two individuals with severe congenital myopathy caused by novel biallelic MYL1 variants." (PMID 40488356, 2025). "It was found that MYL1 is a critical gene for skeletal muscle function and the deficiency of MYL1 related to the severe congenital myopathy." (PMID 33467116, 2021). "Our study confirms that biallelic loss‐of‐function variants in MYL1 are associated with a consistent clinical and histopathological phenotype, which should be considered in individuals with severe congenital myopathy, particularly those with selective hypotrophy of type II fibres." (PMID 40488356, 2025). "Muscle biopsy is recommended in cases of severe congenital myopathy, especially when the genetic diagnosis is unclear, as it can reveal a distinctive myopathological pattern, as the one observed here in association with MYL1 variants." (PMID 40488356, 2025). "Whereas the atrophy or hypotrophy of type I fibres is a common feature in CM, the marked smallness of type II fibres observed in MYL1‐congenital myopathy rarely occurs in genetic myopathies, specifically in MYH2‐related ones." (PMID 40488356, 2025). "Data of individuals with MYL1‐related congenital myopathy were collected in accordance with the ethics guidelines of Hospital Clinico Universitario, Valencia, Hospital Clinic of Barcelona and Hospital Sant Joan de Déu (protocol PIC‐147‐23)." (PMID 40488356, 2025). "Our findings expand the understanding of MYL1‐related congenital myopathy, a condition previously reported only in two individuals of Turkish origin." (PMID 40488356, 2025). "This study aims to advance the understanding of the phenotype and pathogenesis of MYL1‐congenital myopathy." (PMID 40488356, 2025). "The MYL1 gene encodes a fast-twitch regulatory light chain of myosin in skeletal muscle; downregulation of MYL1 alters myocyte morphology and muscle structure, and generates congenital myopathy in zebrafish." (PMID 32000679, 2020). "A notable feature of MYL1 congenital myopathy is the paradoxical preservation of strength in proximal upper limb muscles, rich in fast‐twitch fibres, compared to the poorer performance of lower limbs and axial muscles, which predominantly consist of slow‐twitch type I fibres." (PMID 40488356, 2025).
cardiomyopathy (3 papers, 2014 to 2025). A disease of the heart muscle or myocardium proper. "This work focuses on MYL1 while noting that biallelic MYL2 pathogenic variants cause a myopathy with early onset after birth, leading to progressive cardiomyopathy and early death in infants (OMIM #619424)." (PMID 40488356, 2025).
Cachexia (2 papers, 2020 to 2021). Severe weight loss, wasting of muscle, loss of appetite, and general debility related to a chronic disease. "In addition, SDS-soluble myosin light chain 1 (SDS-MYL1), which indicates maturity of cardiomyocytes, was reduced to 62% in the cachexia group compared to that in the control group." (PMID 33110478, 2020).
head and neck squamous cell carcinoma (1 paper, 2024). A squamous cell carcinoma that arises from any of the following anatomic sites: lip and oral cavity, nasal cavity, paranasal sinuses, pharynx, larynx, and salivary glands. "MYL1, MYL2, and MYL3 were shown to have a positive correlation between expression levels and the infiltration of CD4+T cells in head and neck squamous cell carcinoma (HNSCC)." (PMID 39768172, 2024).
Hernia (1 paper, 2021). "Furthermore, genes from the myosin family, the 1/3 myosin light chain skeletal muscle isoform (MYL1) and myosin light chain 3 (MYL3) have been described as candidate genes to the development of scrotal hernia in pigs, emphasizing the importance of muscle contraction in the development of hernias." (PMID 34773987, 2021).
ischemia (1 paper, 2015). A hypoperfusion of the BLOOD through an organ or tissue caused by a PATHOLOGIC CONSTRICTION or obstruction of its BLOOD VESSELS, or an absence of BLOOD CIRCULATION. "Activated MMP-2 degrades susceptible sarcomeric and cytoskeletal proteins including troponin I (TnI), myosin light chain-1 (MLC-1), and α-actin, leading to the acute contractile dysfunction observed in ischemia/reperfusion injury." (PMID 25559243, 2015).
malnutrition (1 paper, 2024). Inadequate nutrition resulting from poor diet, malabsorption, or abnormal nutrient distribution. "MYL1 plays a crucial role in embryonic skeletal muscle development, and its mutation can result in the loss or malnutrition of type II muscle fibers." (PMID 38396545, 2024).
metabolic myopathies (1 paper, 2014). "VPA alters the expression of PEBP1, BHMT, MYL1, ALB and FLNC that are closely related with metabolic myopathies, myogenesis, albumin gene expression, and haemolytic anemia." (PMID 25551574, 2014).
myocardial infarction (1 paper, 2019). Gross necrosis of the myocardium, as a result of interruption of the blood supply to the area, as in coronary thrombosis. "It has been shown that serum myosin light chain 1 maintains high levels for at least 1 week after myocardial infarction." (PMID 30800662, 2019).
myocardial ischemia (1 paper, 2024). A disorder of cardiac function caused by insufficient blood flow to the muscle tissue of the heart. "Degradation of myosin light chain 1 by gelatinase A during myocardial ischemia–reperfusion and reduced concentration of TnI in the heart tissue has been also demonstrated on our in vivo study, showing the similar mechanism, as was observed in vitro and ex vivo." (PMID 38540247, 2024).
myopia (1 paper, 2024). "Because the retina is a neural tissue, the expression of numerous genes linked to cardiac muscle (MYBPC3, ACTC1, MYL3, MYH7, MYH7B) or to skeletal muscle (MYL1, SMYD1, TNNI2, MYH1B, ACTA1, TNNT3) presents a conundrum for explaining a mechanism for myopia progression." (PMID 39028695, 2024).
rotator cuff tears (1 paper, 2023). "In humans, increased expression of MYL1 has been identified in traumatic rotator cuff tears in female patients, whereas MYL2 is highly expressed in degenerative tears in male patients." (PMID 37645058, 2023).
skeletal myopathies (1 paper, 2025). "However, skeletal myopathies have only been associated with MYL1 and MYL2 genes." (PMID 40488356, 2025).
Stroke (1 paper, 2019). Sudden impairment of blood flow to a part of the brain due to occlusion or rupture of an artery to the brain. "Our proteomics results show that many cytoskeletal proteins were present at higher-than-normal concentrations in CSF following stroke, including myosins (MYH1/4/8/9 and MYL1), and tubulins (TUBA1A/B/C, TUBA3A, and TUBB4A/B)." (PMID 30645580, 2019).
cancer (7 papers, 2019 to 2025). A tumor composed of atypical neoplastic, often pleomorphic cells that invade other tissues. "Regarding the remaining DEPs, Myh4, Acta1, Tnnt3, Mb, Ttn, Actn2, Myh7, Myl1, Mybpc2, Myl3, and Tnnc2 are associated with several cancers." (PMID 39861068, 2024). "The study also highlights the roles of specific proteins (MYH2, MYL1, MYL2, MYH7) and microRNAs (such as hsa-let-7d-5p) that are the potential biomarkers in cancer progression founded on several analyses." (PMID 39656775, 2024). "KEGG analysis revealed significant enrichment of DEGs, including TPM1, MYL1, and MYH3, in pathways such as cytoskeleton in muscle cells, alanine aspartate and glutamate metabolism, cGMP-PKG signaling pathway, central carbon metabolism in cancer, and Th17 cell differentiation." (PMID 41007361, 2025).
tumor (5 papers, 2019 to 2024). "However, the underlying mechanism of MYL1 promoting tumor needs to be further verified." (PMID 37679666, 2023). "We detected MYL1 protein expression levels in tumor and adjacent normal tissue from HSCC patients at stage III or stage IV by using western blot." (PMID 37679666, 2023). "Overall, MYL1 facilitates tumor metastasis and correlates with tumor immune infiltration in HNSCC and these effects may be associated with the EGF/EGFR pathway." (PMID 37679666, 2023). "Finally, we studied the correlation between MYL1 expression level and tumor-infiltrating lymphocytes (TILs) in HNSCC in more detail by using TISIDB." (PMID 37679666, 2023). "MYL1 facilitates tumor metastasis and correlates with tumor immune infiltration in HNSCC and these effects may be associated with the EGF/EGFR pathway." (PMID 37679666, 2023). "The results showed that MYL1 could promote tumor metastasis." (PMID 37679666, 2023). "Recent bioinformatics analyses have also shown that a variety of tumor markers are correlated with tumor immune infiltration in HNSCC, such as PER3, IDO1, MYL1 and HRPT1." (PMID 38937712, 2024). "Compared with the control group, the expression levels of tumor metastasis-related genes EGF and EGFR were significantly increased in the MYL1 overexpression group." (PMID 37679666, 2023). "Myosin genes MYL1, MYL2, MYH2, and MYH7 were proved significantly down-regulated but as unfavorable prognostic markers and related with tumor stages or grades in HNSCC." (PMID 37679666, 2023). "There is a statistical significance of MYL1 or MYH7 promoter methylation level between normal tissues and tumor stage 1–4 or grade 1–4." (PMID 37679666, 2023). "Interestingly, a high expression of the human myosin light chain 1 (MYL1) gene, a tumor-promoting gene, was correlated with tumor immune infiltration and MC infiltration in HNSCC." (PMID 39064602, 2024). "MYL1 promoted HSCC metastasis and correlated with tumor immune infiltration in HNSCC, these functions may be related to the EGF/EGFR signaling pathway." (PMID 37679666, 2023). "The results showed that MYL1 did not affect tumor proliferation." (PMID 37679666, 2023).
myopathies (2 papers, 2023 to 2025). "The findings expand the clinical and pathological spectrum of MYL1‐related myopathy and suggest a broader role for MYL1 in muscle fibre development and maintenance." (PMID 40488356, 2025). "The persistence of developmental myosins in MYL1 myopathy supports this speculation." (PMID 40488356, 2025). "For example, MYL1, MYOM2, TRIM63 and PSMD4 have been broadly associated with myopathies but not directly to LVNC or DCM yet, and could therefore be considered as potential targets to investigate." (PMID 37644440, 2023).
neurodegenerative disease (1 paper, 2025). A disorder of the central nervous system characterized by gradual and progressive loss of neural tissue and neurologic function. "To the best of our knowledge, we detected MYL1 for the first time in the CSF of patients with neurodegenerative diseases, and together with MAP1B and PENK, it has not previously been linked to ALS." (PMID 40681694, 2025).
MYL1 also shares sentences with these, for which no sentence is quoted: dilated cardiomyopathy (1 paper); hyperthyroidism (1); infection (1); muscular dystrophy (1); myocardial disorder (1); myocarditis (1); rhabdomyosarcoma (1); Thrombocytopenia (1).